CASP4 (caspase 4)
Description:
Inflammatory caspase that acts as the effector of the non-canonical inflammasome by mediating lipopolysaccharide (LPS)-induced pyroptosis. Also indirectly activates the NLRP3 and NLRP6 inflammasomes. Acts as a thiol protease that cleaves a tetrapeptide after an Asp residue at position P1: catalyzes cleavage of CGAS, GSDMD and IL18. Effector of the non-canonical inflammasome independently of NLRP3 inflammasome and CASP1: the non-canonical inflammasome promotes pyroptosis through GSDMD cleavage without involving secretion of cytokine IL1B. In the non-canonical inflammasome, CASP4 is activated by direct binding to the lipid A moiety of LPS without the need of an upstream sensor. LPS-binding promotes CASP4 activation and CASP4-mediated cleavage of GSDMD and IL18, followed by IL18 secretion through the GSDMD pore, pyroptosis of infected cells and their extrusion into the gut lumen. Also indirectly promotes secretion of mature cytokines (IL1A and HMGB1) downstream of GSDMD-mediated pyroptosis via activation of the NLRP3 and NLRP6 inflammasomes. Involved in NLRP3-dependent CASP1 activation and IL1B secretion in response to non-canonical activators, such as UVB radiation or cholera enterotoxin. Involved in NLRP6 inflammasome-dependent activation in response to lipoteichoic acid (LTA), a cell-wall component of Gram-positive bacteria, which leads to CASP1 activation and IL1B secretion. Involved in LPS-induced IL6 secretion; this activity may not require caspase enzymatic activity. The non-canonical inflammasome is required for innate immunity to cytosolic, but not vacuolar, bacteria (By similarity). Plays a crucial role in the restriction of S.typhimurium replication in colonic epithelial cells during infection. Activation of the non-canonical inflammasome in brain endothelial cells can lead to excessive pyroptosis, leading to blood-brain barrier breakdown (By similarity). Pyroptosis limits bacterial replication, while cytokine secretion promotes the recruitment and activation of immune cells and triggers mucosal inflammation. May also act as an activator of adaptive immunity in dendritic cells, following activation by oxidized phospholipid 1-palmitoyl-2-arachidonoyl-sn-glycero-3-phosphorylcholine, an oxidized phospholipid (oxPAPC) (By similarity). Involved in cell death induced by endoplasmic reticulum stress and by treatment with cytotoxic APP peptides found in Alzheimer's patient brains. Cleavage of GSDMD is not strictly dependent on the consensus cleavage site but depends on an exosite interface on CASP4 that recognizes and binds the Gasdermin-D, C-terminal (GSDMD-CT) part. Catalyzes cleavage and maturation of IL18; IL18 processing also depends of the exosite interface on CASP4. In contrast, it does not directly process IL1B. During non-canonical inflammasome activation, cuts CGAS and may play a role in the regulation of antiviral innate immune activation. (Microbial infection) In response to the Td92 surface protein of the periodontal pathogen T.denticola, activated by cathepsin CTSG which leads to production and secretion of IL1A and pyroptosis of gingival fibroblasts.
Synonyms: CASP-4; ICH-2; ICE(rel)II; TX; ICEREL-II; Mih1; Mih1/TX
Tractability: Small molecule: a drug acting on it is in phase 2 or 3 trials; a structure with a bound ligand is known; a high-quality ligand is known. Antibody: UniProt places it where antibodies can reach, with high confidence; its Gene Ontology location is reachable by antibodies, with high confidence; the Human Protein Atlas places it where antibodies can reach. PROTAC: ubiquitination databases record sites on it; its protein half-life has been measured; a small molecule that binds it is known.
Target class: Cysteine protease; Protease; Cysteine protease CD clan; Enzyme; Cysteine protease C14 family
Gene: Protein-coding gene on chromosome 11 (104,942,866 to 104,969,366, reverse strand). Ensembl gene ENSG00000196954.
Subcellular location: Cytoplasm, cytosol; Endoplasmic reticulum membrane; Mitochondrion; Inflammasome; Secreted
Subcellular location (Human Protein Atlas): Cytosol; Plasma membrane
Pathways (Reactome):
Immune System: CASP4 inflammasome assembly; CASP4-mediated substrate cleavage; NOD1/2 Signaling Pathway
Disease: Enterobacterial factors antagonize host defense
Programmed Cell Death: Pyroptosis
Gene Ontology:
Molecular function: CARD domain binding; cysteine-type endopeptidase activity; lipid binding; lipopolysaccharide binding; protein binding; cysteine-type peptidase activity
Biological process: cellular response to amyloid-beta; defense response to bacterium; defense response to Gram-positive bacterium; intrinsic apoptotic signaling pathway; intrinsic apoptotic signaling pathway in response to endoplasmic reticulum stress; non-canonical inflammasome complex assembly; positive regulation of inflammatory response; positive regulation of interleukin-18-mediated signaling pathway; positive regulation of tumor necrosis factor-mediated signaling pathway; protein autoprocessing; protein maturation; pyroptotic inflammatory response; regulation of inflammatory response; apoptotic process; positive regulation of neuron apoptotic process; proteolysis; regulation of apoptotic process
Cellular component: canonical inflammasome complex; cytosol; endoplasmic reticulum; endoplasmic reticulum membrane; extracellular region; mitochondrion; non-canonical inflammasome complex; protein-containing complex; cytoplasm; NLRP1 inflammasome complex
Genetic constraint (gnomAD): Loss-of-function variants: 16 observed, 24.78 expected, observed/expected ratio (o/e) 0.65, 90% interval 0.44 to 0.98. The upper end of that interval is the gene's LOEUF score, 0.98, which puts it in group 4 of 6, group 1 being the genes least tolerant of losing a copy. Missense variants: 291 observed, 319.95 expected, observed/expected ratio (o/e) 0.91, 90% interval 0.83 to 1. Synonymous variants: 126 observed, 109.72 expected, observed/expected ratio (o/e) 1.15, 90% interval 0.99 to 1.33.
Homologues: Orthologues: chimpanzee CASP4 (99% identical), macaque CASP4 (96% identical), Caenorhabditis elegans ced-3 (24% identical), zebrafish casp8 (21% identical), tropical clawed frog casp8 (19% identical), zebrafish casp20 (18% identical), Caenorhabditis elegans csp-1 (18% identical), Caenorhabditis elegans csp-2 (18% identical), Drosophila melanogaster Decay (16% identical), Drosophila melanogaster Dronc (16% identical), tropical clawed frog XB5812047 (13% identical), zebrafish casp3l (10% identical), and 1 more. Paralogues in human: CASP5 (73% identical), CASP1 (51% identical), CASP12 (46% identical), CASP2 (23% identical), CASP9 (21% identical), CASP3 (21% identical), CASP7 (19% identical), CASP8 (19% identical), CASP10 (18% identical), CASP6 (17% identical), CASP14 (15% identical), CFLAR (15% identical), and 4 more.
Diseases named in the same sentence as CASP4 in open-access papers:
CASP4 is named in the same sentence as 162 diseases in open-access papers, as found by Europe PMC text mining. Sharing a sentence is not in itself a finding about the gene and the disease. The quoted sentences say what the papers report.
Sepsis (24 papers, 2015 to 2025). Sepsis is defined as life-threatening organ dysfunction caused by a dysregulated host response to infection. "In preclinical models of sepsis, a life-threatening condition caused by a dysregulated host response to infection, signal blockade of CASP4 or CASP11 protected from organ damage and death." (PMID 40670771, 2025). "Aberrant hyper-activation of Casp-4 leads to amplification of the inflammatory response linked to sepsis." (PMID 35458656, 2022). "While such reports highlight the potential benefit of specific inhibition of CASP4/11 for treating sepsis, such CASP4/11-specific inhibitors remain to be identified." (PMID 40670771, 2025). "Control of caspase-11 (caspase 4/-5 in humans) is proven to be a valuable target to interfere with sepsis induced damage, and we show that PLXNC1 holds the potential to control this activity." (PMID 39169397, 2024). "Recently, in sepsis, it was observed that an increased expression of caspase-4/5 is required for endothelial pyroptosis during the development of fulminant pulmonary edema and acute lung injury." (PMID 39770410, 2024). "A recent study in sepsis observed that increased EC expression of caspase-4/5 is required for activation of endothelial pyroptosis, thereby contributing to the development of fulminant pulmonary edema and acute lung injury." (PMID 39770410, 2024). "The study identified seven important PRGs including CHMP7, NLRC4, PLCG1, IRF1, CASP4, NLRP1, GSDMD associated with sepsis." (PMID 37939116, 2023). "We previously found that blocking caspase-11 pathway (human orthologs caspase-4/5) is effective to rescue coagulation-induced organ dysfunction and lethality in sepsis models." (PMID 35982051, 2022). "The function of human CASP4 or CASP5 in sepsis-induced coagulopathy remains poorly understood, but it will be enlightened by these investigations of CASP11 in mouse models." (PMID 33796108, 2021). "This study aimed to identify novel drugs that can control hepatocyte caspase-4/5/11 activation during sepsis." (PMID 34483936, 2021). "Lipopolysaccharide (LPS) promotes caspase-4/5/11 activation, leading to pyroptosis, a major sepsis driver." (PMID 34483936, 2021). "Cytosolic lipopolysaccharide (LPS) sensing by Caspase-4/5/11 for pyroptosis activation is a major driver of the development of sepsis." (PMID 32332915, 2020). "Numerous biological studies related to caspase-4 have found that it plays roles in acute and chronic diseases such as sepsis and cancer." (PMID 30696842, 2019). "The specific inhibition of IL-β production by azithromycin in a murine endotoxin sepsis model, points towards a similar effect on caspase-11, the murine homologue of human caspase-4." (PMID 26152605, 2015). "In addition, LPS-mediated caspase-4/11 signaling also appears in sepsis, diabetes, atherosclerosis, and Alzheimer’s disease in acute and chronic inflammatory conditions." (PMID 40356927, 2025). "Therefore, it is likely that similar mechanisms are involved in cytosolic LPS delivery and caspase-4 and -5 activation in human sepsis." (PMID 35712726, 2022). "In addition, an external GSE185263 dataset was utilized to validate the two genes, and the results showed that the expression of PLCG1 was greatly lower in the sepsis group than in the healthy group, and the expression of CASP4 was higher." (PMID 36250055, 2022). "However, another study pointed out that upregulated GSDMB in patients with sepsis and Crohn’s disease promoted caspase-4 activity and GSDMD cleavage, revealing a GSDMB-regulated novel regulatory mechanism for GSDMD-induced pyroptosis in inflammatory diseases." (PMID 34858408, 2021). "Therefore, desensitizing of cytosolic LPS by Caspase-4/5/11 has been proposed to be a potential therapeutic target for sepsis development." (PMID 32332915, 2020). "Finally, this study only explored caspase-1-dependent pyroptosis, but we still need further study to elucidate the mechanism of other caspases (caspase-4/5/11) activating pyroptosis in sepsis." (PMID 31775794, 2019).
Sepsis (continued). "The induction of caspase-4 (or its mouse homologue caspase-11) protease activity and NLRP3 inflammasome activation are the crucial pathogenic factors in a variety of acute and chronic inflammatory settings including Alzheimer’s disease and sepsis." (PMID 29780528, 2018). "Altogether, our data demonstrate a broader reactivity of caspase-4 to under-acylated LPS than caspase-11, which may have important clinical implications for management of sepsis." (PMID 29339744, 2018). "We identify CASP4 as a bona fide marker of sepsis and ACLF disease severity and propose that it may perform better than currently used markers, given the strong and selective association of CASP4 levels with the most severe condition of immunosuppression and MOF." (PMID 38106412, 2023). "Therefore, targeting human caspase-4 and caspase-5 (caspase 11 in mouse) may be more effective than inhibiting caspase-1 in patients with sepsis." (PMID 34858408, 2021). "According to Sepsis single cell data, two genes, CFLAR and CASP4, were highly expressed in all immune cell subpopulations." (PMID 37007944, 2023). "Compared to that of healthy individuals, the expression level of AIM2, CASP4, NLRC4, and PYCARD was significantly upregulated, while the expression level of PVJK and PLCG1 was significantly downregulated in both sepsis and septic shock patients." (PMID 36250055, 2022). "The canonical and non-canonical inflammasome activation leads to caspase-1 and caspase-4/5/11 activation respectively, with subsequent GSDMD processing as a key regulator mechanism of inflammation during sepsis." (PMID 34996441, 2022). "Our results showed the expression of AIM2, CASP4, NLRC4, and PYCARD was higher and the expression of PVJK and PLCG1 was lower in both sepsis and septic shock patients than in healthy controls." (PMID 36250055, 2022). "In addition, transgenic expression of CASP4 in Casp1−/−/11−/− mice renders increased susceptibility to LPS-induced shock, indicating the pathogenetic role of human non-canonical inflammasome in sepsis." (PMID 33796108, 2021). "We report that CASP4 and CASP5 are differentially regulated during acute-on-chronic liver failure and sepsis-associated immunosuppression, suggesting non-redundant functions in the inflammasome response to infection." (PMID 38106412, 2023). "Our analysis of human monocytes/PBMCs from two independent cohorts of critically ill patients with severe infection illustrates a specific down-regulation of caspase-4, not caspase-5, in sepsis and ACLF." (PMID 38106412, 2023). "In this study, we have explored the regulation of non-canonical inflammasome constituents CASP4, CASP5 and GSDMD during sepsis and acute-on-chronic liver failure (ACLF)-associated immunosuppression." (PMID 38106412, 2023). "Taken together, luteolin has strong anti-inflammatory activity by targeting human caspase-4 and mouse caspase-11 non-canonical inflammasomes in inflammatory responses and immunopathologies, such as gastritis, sepsis, and sepsis-induced ALI." (PMID 37373549, 2023). "Meanwhile, in a clinical study of 20 sepsis patients who received heparin and 21 sepsis patients who did not, activation of caspase-4 (the human homologue of caspase-11) was measured." (PMID 36189354, 2022). "Moreover, differences in the expression of CASP1, CASP3, CASP4, and CASP5 could help distinguish the level of immune cell infiltration in sepsis." (PMID 37939116, 2023). "To understand the role played by the non-canonical inflammasome in this context, we examined CASP4 and CASP5 expression in monocytes from patients with sepsis and organ damage who did or did not exhibit ET." (PMID 38106412, 2023).
glioma (15 papers, 2019 to 2024). A benign or malignant brain and spinal cord tumor that arises from glial cells (astrocytes, oligodendrocytes, ependymal cells). "In general, high CASP4 expression is closely associated with increased numbers of tumor-infiltrating immune cells in gliomas." (PMID 39075190, 2024). "Kaplan–Meier survival curves constructed to differentiate the OS and DFS of the glioma patients showed that CASP4 was strongly associated with OS in glioma patients (P < 0.0001)." (PMID 39075190, 2024). "Although the TIMER immunoassay database showed that CASP4 is closely associated with dendritic cells in glioma patients, the percentage of dendritic cells in glioma immune cells, as revealed by the CIBERSORT algorithm, is very small." (PMID 39075190, 2024). "Relying on comprehensive bioinformatics analyses, we demonstrated that differences in the degree of CASP4 expression are strongly associated with the prognosis of patients with gliomas." (PMID 39075190, 2024). "To describe the level of immune infiltration in gliomas, we further evaluated the association between CASP4 expression and immune cell populations." (PMID 36713560, 2022). "Overall, these results suggest that high CASP4 expression is a risk factor of poor prognosis in patients with glioma." (PMID 36713560, 2022). "CASP4 was highly expressed and associated with a signifificantly lower survival rate in patients with glioma." (PMID 36713560, 2022). "Therefore, our comprehensive analyses indicated that CASP4 is closely associated with cellular pyroptosis, immunotherapy, and drug treatment of gliomas, suggesting the potential of CASP4 as a novel therapeutic target in gliomas." (PMID 39075190, 2024). "Finally, the results of GSEA indicated that CASP4 is involved in the glioma-associated NLRP3-inflammation complex as well as immune signaling pathways such as T cell activation and proliferation and chemokine activation." (PMID 39075190, 2024). "Thus, CASP4 is implicated as a new prognostic biomarker for gliomas with the potential to further guide immunotherapy and chemotherapy strategies for glioma patients." (PMID 39075190, 2024). "In addition, ROC analysis provided a high degree of credibility for the diagnostic value of CASP4 expression in patients with gliomas." (PMID 36713560, 2022). "CASP4 can be a diagnostic biomarker and is a promising therapeutic target for gliomas." (PMID 36713560, 2022). "Therefore, CASP4 expression can be used as a diagnostic molecular marker to evaluate patients with glioma." (PMID 36713560, 2022). "Our study showed that CASP4 expression followed the same trend as macrophage M2 infiltration, suggesting that CASP4 may have an impact on the associated immune cell infiltration, thereby affecting the susceptibility of glioma patients to immunotherapy." (PMID 39075190, 2024). "Similarly, a subgroup analysis in TCGA to analyze the prognostic impact of CASP4 in different glioma grades also showed that high CASP4 expression was associated with poorer OS in WHO G3 (HR = 1.97, 95% CI = 0.93–4.07, Cox P = 0.004) and WHO G4 (HR = 1.42, 95% CI = 1.01–2.00, Cox P = 0.044)." (PMID 36713560, 2022). "Using the CIBERSORT algorithm, we found that M2 type macrophages were not only present at a high percentage, but also exhibited greater infiltration of gliomas expressing high levels of CASP4." (PMID 39075190, 2024). "We then investigated the importance of CASP4 using Kaplan–Meier survival analysis of glioma patients." (PMID 39075190, 2024). "We explored the relationship between CASP4 and tumor behavior, tumor subtype, and other clinical features of gliomas." (PMID 39075190, 2024). "In our study, we targeted the key gene CASP4 in a differential analysis of pyroptosis-related genes in gliomas and their relationship to clinical prognosis." (PMID 39075190, 2024).